LGALS1 (galectin 1)
Diseases named in the same sentence as LGALS1 in open-access papers (continued):
Sharing a sentence is not in itself a finding about the gene and the disease.
Obesity (25 papers, 2018 to 2026). Accumulation of substantial excess body fat. "High serum levels of galectin-1 observed in obesity, is a risk factor for developing T2D over time and is associated with poor outcome in several malignant cancers including prostate cancer and ovarian cancer." (PMID 38578722, 2024). "There was a clear distinction between the two galectins when comparing the association profiles and the Imiomics analysis for galectin-1 and galectin-3 on measures of obesity and adipose tissue distribution." (PMID 38777863, 2024). "Galectin-1 is a β-galactoside binding protein with functions in metabolism and inflammation and it has been linked to obesity and type II diabetes." (PMID 39217505, 2024). "The association between galectin-1 and adiposity also complicates the analysis of other variables related to obesity, as there is a risk in over-adjusting the linear models." (PMID 38777863, 2024). "Circulating galectin-1 was also associated with obesity in several studies in both humans and in obese animal models." (PMID 36295832, 2022). "Like galectin-1, leptin is closely associated with obesity and these proteins are also associated with each other." (PMID 36295832, 2022). "Taken together, studies on human and animal models demonstrate the close association between galectin-1 and pathophysiological processes related to obesity, insulin resistance, and T2D." (PMID 36295832, 2022). "Taken together, these studies suggest that galectin-1 is not only associated with obesity, but also has a functional role in adipose tissue physiology and regulation of fat mass homeostasis." (PMID 36295832, 2022). "Galectin-1 is implicated in tumor development and in obesity, and the galectin-1 inhibitor thiodigalactoside reduced the body weight gain in mice." (PMID 29950926, 2018). "Moreover, LGALS1 expression has been reported to be decrease in participants with obesity during weight loss while increased during weight gain." (PMID 38703299, 2024). "Here, we seek to assess the association profiles of galectin-1 and galectin-3 to glucose homeostasis and different obesity-related variables in the cross-sectional, population-based Prospective investigation of Obesity, Energy and Metabolism (POEM) cohort study from Sweden." (PMID 38777863, 2024). "Previous studies have demonstrated a correlation between serum galectin-1 levels and obesity and IR." (PMID 40002838, 2025). "The association profiles for galectin-1 and galectin-3 indicate overlapping metabolic effects in humans, while the distinctly different associations seen with fat mass, fat distribution, and adipose tissue differentiation markers may suggest a functional role of galectin-1 in obesity." (PMID 38777863, 2024). "Galectin-1 plays a functional role in human metabolism and the levels are altered in obesity and type 2 diabetes (T2D)." (PMID 38578722, 2024). "In this regard, LGALS1 was found increased on SAT of individuals with obesity in two different studies in the present systematic review." (PMID 38703299, 2024). "The Lgals1 gene plays an important role in adipocyte differentiation and the development of obesity, particularly through its interaction with and influence on the activity of PPARγ." (PMID 39040415, 2024). "In recent years, animal and human studies highlighted galectin-1 in several diseases, including obesity, type 2 diabetes (T2D), cancer, cardiovascular and muscle diseases." (PMID 38578722, 2024). "Plasma galectin-1 was suppressed by LPS treatment and obesity and IL-6−/− knockout modulated the response." (PMID 36295832, 2022). "Here, we review pre-clinical and clinical knowledge surrounding galectin-1 in obesity, its relation to mechanisms in insulin resistance with emphasis on clinical studies in T2D and its complications." (PMID 36295832, 2022). "Several proteomic studies have independently identified an increased galectin-1 expression in the adipose tissue in obesity and in insulin resistance." (PMID 36295832, 2022).
Obesity (continued). "In line with this, animal studies have assessed the feasibility of modulating galectin-1 as a treatment alternative in obesity and complications in T2D." (PMID 36295832, 2022). "Here, we review the current knowledge on the clinical potential of galectin-1 in obesity and type 2 diabetes." (PMID 36295832, 2022). "Studies including high-fat diet (HFD) or ob/ob mice (leptin knockout mice, a classic model to study obesity in animal models) have all presented increased galectin-1 in the adipose tissue." (PMID 36295832, 2022). "It has been shown that galectin-1 increases in obesity, both in the circulation and in the adipose tissue of human and animal models." (PMID 36295832, 2022). "While observational studies in humans largely align with interventional studies in animal models, it is now important to further validate the potential of intervening with galectin-1 activity as a therapeutic strategy in obesity and T2D in humans." (PMID 36295832, 2022). "In recent years, increasing evidence has emerged for the role of galectin-1 in obesity, insulin resistance and type 2 diabetes." (PMID 36295832, 2022). "It suggested that depletion of galectin-1 increased thermogenic gene expression to lead resistance to obesity." (PMID 33431823, 2021). "In light of our results, the development of galectin-1 inhibitors should be considered as a therapeutic strategy for obesity and other metabolic diseases." (PMID 33431823, 2021). "Collectively, galectin-1 exacerbates obesity of mice fed HFD by increment of PPARγ expression and activation." (PMID 33431823, 2021). "In a cohort of approximately 1000 middle-aged subjects observed in the population, serum galectin-1 concentrations independently predicted obesity and insulin resistance, indicating that galectin-1 represents the level of adipose dysfunction and metabolic dysregulation." (PMID 41590667, 2026). "As galectin-1 can be an agent in obesity released from the adipocytes to regulate metabolic actions, adjusting for BMI might introduce bias to the analysis." (PMID 38777863, 2024). "Emerging evidence suggests that another lectin, galectin-1, could have an equal or even more significant role in obesity and metabolic disease." (PMID 38777863, 2024). "Additionally, both galectin-1 and galectin-3 were associated with IL-10 and TNF signaling, pathways previously related to galectins and with a role in obesity-related inflammation and lipid metabolism." (PMID 38777863, 2024). "Going forward, advancing the knowledge around galectin-1 in obesity and metabolic disease could further shed light on the pathophysiology of T2D and its complications and help to find out whether galectin-1 has potential as a biomarker in prediabetes and T2D." (PMID 36295832, 2022). "Galectin-1 modulates inflammation and angiogenesis, and cross-sectional studies indicate that galectin-1 may be a uniting factor between obesity, type 2 diabetes and kidney function." (PMID 34743218, 2022). "The strong association between galectin-1 and body mass could indicate that elevated levels of galectin-1 reported in obesity are largely explained by cells in the adipose tissue." (PMID 36295832, 2022). "The altered regulation of galectin-1 in obesity and metabolic disease could therefore also have an impact on several complications related to T2D." (PMID 36295832, 2022). "The role of galectin-1 in obesity has also been also explored." (PMID 33431823, 2021). "Our findings suggest that galectin-1 could be a potential therapeutic target for obesity and needed further study for clinical application." (PMID 33431823, 2021). "It is unclear whether this result reflects direct regulation by galectin-1 or an additional effect of obesity resistance." (PMID 33431823, 2021). "Indeed, pharmacological inhibition of Lgals1 was shown to alleviate adiposity in obesity." (PMID 35406736, 2022). "Therefore, we explored the mechanism by which galectin-1 regulates adipogenesis and obesity." (PMID 33431823, 2021).
Obesity (continued). "In addition to the dysregulation of monocytes and macrophages, obesity also compromises the immune function of memory T cells through upregulation of galectin-1 that functions to inhibit T-cell-mediated immunity and promote tumor angiogenesis (hypothesis 2)." (PMID 32785175, 2020). "This analysis showed that some proteins, such as COL1A1, COL6A3, FABP4, LEP, LGALS1, and THBS4, are obesity-specific, and GDF15, LPL, MCFD2, REG1A, REG1B, and TCN2 are T2D-specific." (PMID 38732002, 2024). "However, the exact function of galectin-1 in the context of obesity is still unknown." (PMID 33431823, 2021). "The results of the other study showed that when mice lacked the Lgals1 gene, they showed a degree of resistance to high fat diet-induced obesity." (PMID 39040415, 2024). "The authors concluded that galectin-1 levels were proportional to the fat mass in children with obesity but not in the lean group." (PMID 36295832, 2022). "Lgals1 (galectin-1) was also highly upregulated in the livers of DIO mice, which is in agreement with a previous study that showed increased Lgals1 expression in obesity." (PMID 35406736, 2022). "In memory T cells, expression of Lgals1 and S100a6 genes was upregulated by HFD-induced obesity." (PMID 32785175, 2020).
diabetes (22 papers, 2014 to 2025). "Several studies have demonstrated a role of galectin-1 in the development of kidney disease, specifically linked to diabetes, but also in other contexts." (PMID 36295832, 2022). "Several studies have also linked galectin-1 to the progression of complications in diabetes, including kidney disease and retinopathy." (PMID 36295832, 2022). "The association between galectin-1 and eGFR was also examined in individuals with newly diagnosed diabetes from the All New Diabetics In Scania (ANDIS) cohort." (PMID 34743218, 2022). "In the context of metabolic control and loss of the same in, for example, diabetes, galectin-1, -2, -3, -9, and -12 are especially interesting." (PMID 29950926, 2018). "High plasma galectin-1 level has been reported to be a significant predictor of renal function decline, independently of diabetes and other risk factors, in a longitudinal study of 798 individuals who underwent elective coronary angiography or percutaneous coronary intervention." (PMID 36295832, 2022). "However, longitudinal evidence on the association between galectin-1 and diabetes risk remains to be shown." (PMID 34743218, 2022). "We hypothesized that elevated galectin-1 levels, which have been reported to be associated with diabetes and diabetic nephropathy, would also be predictive markers of CIN and renal function decline in these patients." (PMID 31996694, 2020). "This study aims to evaluate the diagnostic value of serum galectin-1 for MASLD, given its strong correlation with insulin resistance (IR) and diabetes mellitus (DM)." (PMID 40002838, 2025). "We also show that individuals with type 2 diabetes in the SIRD cluster in the ANDIS study have higher galectin-1 levels compared with other diabetes clusters and that individuals in the SIRD group with higher galectin-1 have lower eGFR." (PMID 34743218, 2022). "TSC22D3 inhibits hypoxia- and diabetes-induced galectin-1 expression due to hypoxia and diabetes by disrupting the stability of the HIF-1α protein." (PMID 36466094, 2022). "Previous studies have also reported that galectin-1 levels increase in eyes of individuals with diabetes after accumulation of d-AGEs, as a direct response to the induced inflammation." (PMID 34743218, 2022). "Participants with a parental history of diabetes mellitus had lower levels of galectin-1, and similarly, participants with prevalent diabetes mellitus also had lower galectin-1 levels after adjustment for age, sex and BMI." (PMID 34743218, 2022). "Similar to previous findings, participants with prevalent diabetes mellitus at baseline in our study had lower galectin-1 levels after adjustment for BMI." (PMID 34743218, 2022). "Recent results suggest galectin-1 (Gal-1) as a new possible therapeutic target for fibrosis in diabetes." (PMID 35897964, 2022). "Further studies focusing on the role of galectin-1 in glucose homeostasis will be necessary to clarify the impact of galectin-1 on diabetes." (PMID 33431823, 2021). "In univariate logistic regression analysis, a higher galectin-1 level, older age, history of diabetes, lower hemoglobin level, decreased baseline eGFR, and presence of proteinuria were associated significantly with a greater risk of CIN." (PMID 31996694, 2020). "Patients with higher galectin-1 concentrations were older; had greater prevalence of hypertension, diabetes, chronic kidney disease, and heart failure; and were more likely to present with higher hs-CRP levels and SYNTAX scores." (PMID 33244142, 2020). "Given that the HIF‐1 pathway is activated in the retina of mice with streptozotocin‐induced diabetes, we performed in vivo experiments to further verify the inhibitory effect of glucocorticoids on hypoxia‐induced galectin‐1/LGALS1 expression in vitro." (PMID 32150332, 2020). "Patients with higher plasma galectin-1 concentrations were older and had higher incidences of hypertension, diabetes, CKD, heart failure, and multiple vessel disease." (PMID 31996694, 2020).
diabetes (continued). "Administration of glucocorticoids to mice attenuated diabetes‐induced retinal galectin‐1/Lgals1 expression together with AKT/AP‐1 and ERK/AP‐1 pathways." (PMID 31328390, 2019). "In vivo administration of glucocorticoids to mice attenuated diabetes‐induced retinal galectin‐1/Lgals1 expression together with AKT/AP‐1 and ERK/AP‐1 pathways." (PMID 31328390, 2019). "Since both administration of galectin-1 and inhibition of it can be beneficial, studies need to be holistic and body weight, diabetes, and cancer should be monitored in further work." (PMID 29950926, 2018). "In vivo inhibition of AGE generation with aminoguanidine, depletion of macrophages with clodronate liposomes, and antibody-based blockade of Il-1β and Tlr4 significantly attenuated diabetes-induced retinal Lgals1 expression in mice." (PMID 29170525, 2017). "To further investigate protein expression and tissue localization of Il-1β and galectin-1 in the retina of mice with STZ-induced diabetes, we performed double-staining immunofluorescence." (PMID 29170525, 2017). "Lgals1 expression levels increased in the retina of mice with STZ-induced diabetes at 2 months compared to citrate buffer as a vehicle control (fold change = 3.16), in accordance with the elevated protein concentration." (PMID 29170525, 2017). "This is consistent with the current data showing the unelevated levels of galectin-1 in non-diabetic retinal vascular occlusions CRVO and BRVO, both of which are governed by hypoxia-induced VEGF." (PMID 29170525, 2017). "In vivo inhibition of AGE generation with aminoguanidine, macrophage depletion with clodronate liposomes, and antibody-based blockade of Il-1β and Tlr4 attenuated diabetes-induced retinal Lgals1 expression in mice." (PMID 29170525, 2017). "The anti-inflammatory properties of galectin-1 have been examined in several states of chronic inflammation and autoimmunity including autoimmune encephalomyelitis, arthritis, colitis, hepatitis, diabetes and chronic pancreatitis." (PMID 25473847, 2014). "Before adjustment for diabetes, tertile 3 of the galectin-1 level correlated with CIN." (PMID 31996694, 2020). "Increasing galectin-1 concentrations were associated significantly with renal function decline, irrespective of underlying diseases, such as diabetes and proteinuria, or of PCI status (pinteraction > 0.05)." (PMID 31996694, 2020). "In a univariate Cox regression analysis, older age, histories of hypertension and diabetes, proteinuria, higher serum galectin-1 level, lower hemoglobin level, reduced eGFR, and lower LVEF, as well as prior CIN, were associated significantly with a higher incidence of renal function decline." (PMID 31996694, 2020). "Our findings, in agreement with previous reports, illustrate the association of galectin-1 with renal function decline irrespective of diabetes." (PMID 31996694, 2020). "In addition, recent evidence has revealed that galectin-1 is a fibrosis protein that is highly expressed in the kidneys of mice with types 1 and 2 diabetes, and activated in proximal tubular epithelial cells under high-glucose conditions." (PMID 31996694, 2020). "For galectin-1 and galectin-9, an increase in the levels of the proteins could protect against diabetes, whilst for galectin-12 inhibition of the protein could be protective." (PMID 29950926, 2018). "Galectin-1 levels increase in eyes of patients with diabetes after accumulation of AGEs, and vitreous aspirates from eyes of patients with diabetic macular edema and later proliferative diabetic retinopathy have increased galectin-1 levels." (PMID 29950926, 2018). "Intravitreal injections of anti-Il-1β and anti-Tlr4 neutralizing antibodies to animals with STZ-induced diabetes significantly reduced retinal Lgals1 expression (anti-Il-1β, fold change = 1.96; anti-Tlr4, fold change = 1.41) compared to normal IgG treatment (fold change = 3.55)." (PMID 29170525, 2017).